CXCL1 (C-X-C motif chemokine ligand 1)
Diseases named in the same sentence as CXCL1 in open-access papers (continued):
Sharing a sentence is not in itself a finding about the gene and the disease.
atrial fibrillation (4 papers, 2022 to 2025). A disorder characterized by an electrocardiographic finding of a supraventricular arrhythmia characterized by the replacement of consistent P waves by rapid oscillations or fibrillatory waves that vary in size, shape and timing and are accompanied by an irregular ventricular response. "Some studies have pointed out that CXCL7/PPBP and CXCL1 are the hub genes with the most associations in atrial fibrillation." (PMID 40078458, 2025). "In addition, CXCL7/PPBP and CXCL1 are the hub gene in atrial fibrillation with the highest number of associations." (PMID 36613652, 2022). "The expression level of CXCL1 in the atrium of atrial fibrillation patients is strongly positively correlated with activated mast cells, which is consistent with the results of immune infiltration analysis in this study." (PMID 40078458, 2025). "This suggests that if CXCR2 has a role in the pathogenesis of atrial fibrillation, then it is activated by a ligand other than CXCL1." (PMID 36613652, 2022). "The level of CXCL1 expression in the atrium in patients with atrial fibrillation is strongly positively correlated with activated mast cells, weakly positively correlated with M2 macrophages and negatively correlated with M1 macrophages." (PMID 36613652, 2022). "At the same time, atrial fibrillation patients have lower CXCL1 expression in the atrium heart tissue and higher CXCR2 expression compared to healthy subjects." (PMID 36613652, 2022). "Patients with atrial fibrillation have higher levels of CXCL1 and CXCR2+ monocytes in their blood." (PMID 36613652, 2022).
bladder tumor (4 papers, 2013 to 2025). "For example, bladder tumor cells secrete CXCL1 and CXCL8, which recruit neutrophils and activate the ERK and JNK signaling pathways." (PMID 40739091, 2025). "In vivo, it was shown that CXCL1 secreted by TAMs and CAFs enhanced bladder tumor cell attachment to the bladder wall, consequently inducing tumor growth." (PMID 36699696, 2022). "They contribute to an increase in bladder tumor cell proliferation and viability by the secretion of CXCL1 and collagen-I." (PMID 34572939, 2021). "We report the first large-scale study assessing CXCL1 protein expression in human bladder tumor tissues." (PMID 23815949, 2013). "However, in bladder tumor tissues, CXCL1 staining was observed in 40% of pTa tumors as well as 75% of pT1-4 tumors and its expression was increased with tumor stage and grade." (PMID 34572939, 2021). "Increased expression of CXCL1 was evident in higher grade and higher stage bladder tumors." (PMID 23815949, 2013). "While no previous CXCL1 protein studies had been reported in bladder tumors, a number of studies have profiled the BCa transcriptome." (PMID 23815949, 2013).
Candida infection (4 papers, 2011 to 2025). "CXCL1 is also mediated for host defense against C. albicans infection, with a previous study showing increased CXCL1 expression in TRAF1-deficient mice, leading to neutrophil recruitment and resulting in Candida infection reduction." (PMID 41294483, 2025). "Murine CXCL1, a homolog of human IL-8, was dramatically induced in WT mice following Candida infection and levels were significantly reduced in all strains of inflammasome deficient mice." (PMID 22174673, 2011). "Ocular concentrations of IL-6, CXCL1/KC, CXCL2/MIP-2, and CCL2/MCP-1 were significantly elevated during C. albicans infection compared with non-albicans Candida infection by the reference strains." (PMID 30386320, 2018).
cervical squamous cell carcinoma (4 papers, 2017 to 2023). A squamous cell carcinoma arising from the cervical epithelium. "It has been observed that the level of CXCL1 in the serum of patients with squamous cell cervical cancer in stage II and stage III is higher than in stage I." (PMID 37108425, 2023). "The data showed a significant increase in IDO1, CXCL1, and CXCL8 mRNA expression in cervical squamous cell carcinoma and endocervical adenocarcinoma (CECS)." (PMID 37626777, 2023). "In another example, cervical squamous cell carcinoma and endocervical adenocarcinoma exhibited a negative correlation between the expression of CXCL1, CXCL6, and CXCL8 and EMT, whereas the expression of CXCL3, CXCL5, and PPBP positively correlated with EMT." (PMID 37686093, 2023). "Interestingly, one of these factors, CXCL1 (also named as growth regulated oncogene 1, GRO-1), its serum levels were significantly higher in patients with cervical squamous cell carcinoma (CSCC) when compared with patients with cervical intraepithelial neoplasia (CIN) and the healthy controls." (PMID 28415759, 2017).
cervical tumors (4 papers, 2021 to 2023). "In regard to CXCL1, it has been reported with an increased expression in cervical tumors, as well as in the serum of CC patients." (PMID 37893029, 2023). "The great significance of CXCL1 in tumorigenesis is confirmed by the correlation between patient prognosis and the level of CXCL1 expression in cervical tumors." (PMID 37108425, 2023). "In Zhai cervix statistics, CXCL1/3/5/6/8/13 were overexpressed in cervical tumor tissues versus tumor-adjacent tissues." (PMID 34321012, 2021). "CXCL1 expression is higher in cervical tumors relative to healthy tissue." (PMID 37108425, 2023).
cholangiocarcinoma (4 papers, 2021 to 2025). A carcinoma that arises from the intrahepatic biliary tree (intrahepatic cholangiocarcinoma) or from the junction, or adjacent to the junction, of the right and left hepatic ducts (hilar cholangiocarcinoma). "In cholangiocarcinoma, in vitro experiments revealed that CXCL1 inhibits the proliferation of OCUG-1 and HuCCT1 tumor cells." (PMID 37686093, 2023). "An in vitro study has shown, CXCR2 ligands, particularly CXCL1, inhibit the migration of cholangiocarcinoma cells." (PMID 37686093, 2023). "Studies of patients with cholangiocarcinoma have shown that this is one of the few cancers in which CXCL1 may have anticancer properties." (PMID 37408240, 2023). "CXCL1 may also have pro-cancer properties in cholangiocarcinoma." (PMID 37408240, 2023). "The source of CXCL1 in cholangiocarcinoma tumors may be mesenchymal stem cells (MSC), as cancer cells secrete extracellular vesicles that act on MSC, causing their fibroblastic differentiation and increasing the expression of secretory factors such as CXCL1, CCL2, and IL-6." (PMID 37408240, 2023). "CXCL1 inhibits the proliferation of OCUG-1 and HuCCT1 cholangiocarcinoma cells and does not affect the proliferation of KMBC cells." (PMID 37408240, 2023).
Chronic colitis (4 papers, 2020 to 2023). A chronic inflammatory disease of the large intestine (colon, cecum and rectum). "This work found that chronic colitis resulted in increased myeloperoxidase activity in the colon, as well as increased levels of proinflammatory cytokines IL-1β and CXCL1." (PMID 37512580, 2023). "The data from the present study also showed that the plasma levels of proinflammatory cytokines, G-CSF, IL-6, IL-17, TNF-α, and CXCL1, were significantly increased in mice with chronic colitis, suggesting the presence of significant systematic inflammation in mice with chronic colitis." (PMID 36009796, 2022).
chronic kidney disease (4 papers, 2012 to 2023). Impairment of the renal function secondary to chronic kidney damage persisting for three or more months. "CXCL1 has also been associated with various inflammatory kidney diseases such acute kidney ischemia and glomerulonephritis and progression of chronic kidney disease." (PMID 32256495, 2020). "The top 25 upregulated genes showed evidence of matrix protein replacement with increased collagen synthesis (Col1a1 and Col3a1) and cellular infiltration (Cxcl1, Lyzs, Ccl5, Lyz2, Lyz, C3 VCAM1 and Ear2), consistent with the histological presence of chronic kidney disease in the mice." (PMID 22970174, 2012).
colorectal adenocarcinoma (4 papers, 2016 to 2025). The most common type of colorectal carcinoma. "Patients with colorectal adenocarcinoma, the majority of whom would be expected to harbor APC mutations, showed upregulated CXCL1, 2, and 3 expression at early stages of disease." (PMID 40545113, 2025). "In this manuscript, we have extensively examined expression and prognosis of CXCL1 gene in colorectal adenocarcinoma (COAD) using different cases of colorectal adenocarcinoma and tissues." (PMID 35958781, 2022). "We also interrogated the co-expression of the reported genes on the same data set (17157 genes from 244 colorectal adenocarcinoma cases); strikingly, IL1B, IL8 and CXCL1 display the highest correlation with IL1A, with a Pearson correlation of 0.66, 0.55 and 0.51 respectively." (PMID 27708224, 2016).
contact dermatitis (4 papers, 2015 to 2024). An inflammatory skin condition caused by direct contact between the skin and either an irritating substance or an allergen. "In a mouse model of contact dermatitis, decorin deficiency resulted in the reduced expression of chemokines, including KC/CXCL-1 and MCP-1/CCL2, and attenuated leukocyte recruitment." (PMID 25781946, 2015). "In a mouse model of irritant contact dermatitis induced by croton oil, topically applied recombinant human TRX significantly suppressed the inflammatory response by inhibiting the production of cytokines and chemokines, such as Tnf-α, Il-1β, Il-6, Cxcl1, and Mcp-1, in the skin tissues." (PMID 32244938, 2020).
coronary artery disease (4 papers, 2012 to 2025). "Recent data demonstrated the enhanced expression of CXCL1 and its receptor (CX3CR1) in coronary artery disease that could be downmodulated by statin therapy." (PMID 24307998, 2013).
diabetic nephropathy (4 papers, 2020 to 2023). "The results showed that both CCL5 and CXCL1 were upregulated in diabetic nephropathy patients and were associated with a decline in renal function." (PMID 37189669, 2023). "The results implied that CXCL1/CXCR2 mediated inflammation may play a vital role in the occurrence and development of diabetic nephropathy." (PMID 34975537, 2021).
E. coli infection (4 papers, 2019 to 2023). "However, the CXCL1/2 release as a result of L. monocytogenes and E. coli infections was much slower." (PMID 34899755, 2021).
endometrial adenocarcinoma (4 papers, 2009 to 2021). "Exogenous administration of PGF2α upregulates the expression of C-X-C motif chemokine ligand 1 (CXCL-1), which is a chemoattractant for neutrophils and promotes neutrophil chemotaxis in endometrial adenocarcinoma." (PMID 34884648, 2021). "Furthermore we have recently shown that CXCL1 expression is elevated in endometrial adenocarcinomas and promotes neutrophil chemotaxis via PGF2α-FP receptor signaling to extracellular signal-regulated kinase." (PMID 19819266, 2009). "Furthermore we found that PGF2α-F-prostanoid (FP) receptor regulates the expression of the CXCR2 ligand CXCL1, to promote neutrophil chemotaxis in endometrial adenocarcinomas." (PMID 19819266, 2009). "They further showed that CXCL1 and CXCR2 expression was elevated in the cancer tissue and that PGF2α‐FP receptors signalling promotes CXCL1 expression on endometrial adenocarcinoma cells and attracts CXCR2‐expressing neutrophils." (PMID 30381825, 2019). "In addition, CXCL1 and CXCL8 are chemokines that are elevated in endometrial adenocarcinoma." (PMID 30813939, 2019).
endothelial dysfunction (4 papers, 2018 to 2025). In vascular diseases, endothelial dysfunction is a systemic pathological state of the endothelium (the inner lining of blood vessels) and can be broadly defined as an imbalance between vasodilating and vasoconstricting substances produced by (or acting on) the endothelium. "Upon recruitment to inflamed endothelium via chemokines such as CXCL1 and CXCL8, neutrophils exacerbate vascular inflammation by releasing pro-inflammatory cytokines, including IL-1β, IL-8, and tumor necrosis factor-α (TNF-α), which amplify endothelial dysfunction and promote monocyte adhesion." (PMID 40217958, 2025).
endotoxemia (4 papers, 2020 to 2024). "Finally, we identified and verified 9 key genes (Cd274, Cxcl1, Cxcl9, Icam1, Ifit2, Isg15, Stat1, Tlr2, and Usp18), and we predicted seven potential drugs for multi-organ damage in LPS-induced endotoxemia." (PMID 33330617, 2020).
gastric tumor (4 papers, 2010 to 2024). "In turn, the chemokine CXCL1 mediates tumor–stroma interaction, regulates gastric tumor invasion, and promotes local tumor growth through activation of the VEGF pathway." (PMID 36613737, 2022). "The expression levels of CXCR4 and NFE2L2 as well as four differentially expressed NRGs (SPP1, CXCL1, MMP9, and TIMP1) were validated in gastric tumor cells and clinical samples." (PMID 38221932, 2024). "Gene ontology analysis of gene expression in the gastric tumors indicates that PPARδ, MMP12, MMP13, Cxcl1, Cxcl5, S100A8, and S100A9 share both common and disparate pathway interactions that likely contributed to the tumorigenic phenotype." (PMID 21318167, 2010). "We also note that the expression of several angiogenesis-related genes (Cxcl1, Cxcl2, Mmp2, Mmp9, and Vegf) was comparable among gastric tumor and non-tumor tissues from 3mo and 6mo gp130F/F and gp130F/F:Nlrp3-/- mice." (PMID 35299732, 2022).
glomerulonephritis (4 papers, 2016 to 2021). A renal disorder characterized by damage in the glomeruli. "CXCL-1 is known as being able to induce inflammatory events via neutrophil migration and has been detected in lung inflammation, glomerulonephritis, and inflammatory exudates induced by LPS." (PMID 27579035, 2016).
head and neck cancer (4 papers, 2020 to 2025). A primary or metastatic malignant neoplasm affecting the head and neck. "High levels of CXCL1 in the blood of patients with head and neck cancer are associated with failure of radiation therapy." (PMID 37408240, 2023). "Other secretory factors that can increase CXCL1 expression in head and neck cancer cells are interleukin-1α (IL-1α) and epidermal growth factor (EGF), as suggested by experiments in mouse models." (PMID 37408240, 2023). "Specifically, OTSCC cancer cells cause an increase in CXCL1 expression in lymphatic endothelial cells (LEC), which leads to head and neck cancer cells migrating into LEC, and consequently cancer cells migrating into lymphatic vessels and lymph node metastasis." (PMID 37408240, 2023). "CXCL1 is secreted by cancer cells in head and neck cancer including OSCC cells." (PMID 37408240, 2023). "CXCL1 is also involved in tumorigenesis in head and neck cancer." (PMID 37408240, 2023). "CXCL1 may be involved in the development of head and neck cancer, as its expression is elevated in fibroblasts during oral submucosal fibrosis, a precancerous condition that can lead to head and neck cancer." (PMID 40490643, 2025). "CXCL1 may contribute to the formation of head and neck cancer." (PMID 37408240, 2023). "In patients with head and neck cancer, blood CXCL1 levels may be lower than in healthy individuals." (PMID 37408240, 2023). "CXCL1 may also be responsible for the recruitment of TAN into the head and neck cancer tumor niche." (PMID 37408240, 2023). "Other significantly elevated cytokines detected in the saliva of head and neck cancer patients included CX3CL1, CCL2, CXCL1 and CCL15, most of which correlated with UWS secretion rates and objective oral dryness (CODS)." (PMID 32911805, 2020).
keloid (4 papers, 2018 to 2021). An irregularly shaped, elevated mark on the skin caused by deposits of excessive amounts of collagen during wound healing. "CXCL1 expression is increased in keloids and promotes keratinocyte migration." (PMID 33889572, 2021). "Although shikonin inhibited the overproduction of IL-6 in keloid cells, it did not normalize the production of CXCL1." (PMID 34143844, 2021). "Furthermore, while most keloid histology does not indicate a strong role for neutrophils, the stark reduction in neutrophil chemokines like CXCL1 may indicate a role for neutrophils early in the tissue repair pathology such as seen in other disorders." (PMID 34143844, 2021).
kidney inflammation (4 papers, 2013 to 2024). "Our data shows the critical role which the chemokine CXCL1 plays in cisplatin-induced kidney inflammation, while also providing an opportunity for the evaluation of therapeutic interventions based on this, and other inflammatory biomarkers, in AKI." (PMID 39192240, 2024). "Therefore, although urinary CXCL1 cannot be used as a fully specific biomarker for IgAN among patients with primary nephritis, those with IgAN showed significantly higher urinary CXCL1 levels." (PMID 25816025, 2015). "We also found that chemokines attracting neutrophils such as Cxcl1, -4, -5 and IL-8 were down regulated by p38α during anti-GBM nephritis." (PMID 23441175, 2013).
lupus (4 papers, 2021 to 2025). "Therefore, the chemokine CXCL1 may be implicated in the pathogenesis/inflammatory process in lupus." (PMID 34961474, 2021). "By RNA-Seq, we found that gene expression of local chemokines in the kidney of lupus-prone mice was altered, and qRT-PCR further confirmed down-regulated expression of CXCL1, CCL2, and CXCL10 in the kidney of IL-22 or IL-22R KO MRL/lpr mice compared with MRL/lpr mice." (PMID 33717066, 2021). "Likewise, CXCL1 was mainly involved in chemokine signaling pathway, cytokine-cytokine receptor interaction, graft versus host disease, leishmania infection, primary immunodeficiency, and systemic lupus erythematosus." (PMID 37266443, 2023). "Additionly, serum CXCL1 concentrations were related to different disease activity levels in SLE and lupus nephritis (LN) and high avidity of IgG ANAs (HA IgG ANAs) (p < 0.05)." (PMID 34961474, 2021). "The purpose of our study was to evaluate the regulatory response of CXCL1 in the serum of patients with systemic lupus erythematosus (SLE) in the active stage of disease and to assess whether it was implicated in the pathogenesis/inflammatory process in lupus." (PMID 34961474, 2021).
lymphoma (4 papers, 2018 to 2025). A malignant (clonal) proliferation of B- lymphocytes or T- lymphocytes which involves the lymph nodes, bone marrow and/or extranodal sites. "The changes in the mRNA expression levels of CXCL1, CXCL3-8 and CXCL17 in lymphoma patients were not particularly significant (P > 0.05)." (PMID 35181719, 2022).
metastatic disease (4 papers, 2008 to 2025). "Increased plasma levels of CXCL1 protein are associated with decreased survival of patients with metastatic disease." (PMID 25344051, 2014). "We found a marked production of CCL2 and CXCL1 in the lung, in parallel with macrophage influx, increased metastatic disease and high versican expression in the lung tissue." (PMID 31334111, 2019).
metastatic melanoma (4 papers, 2009 to 2022). A melanoma that has spread from its primary site to another anatomic site. "Among these chemokines CXCL1 has been associated with metastatic melanoma." (PMID 31920649, 2019).
metastatic prostate carcinoma (4 papers, 2014 to 2022). A carcinoma that arises from the prostate gland and has spread to other anatomic sites. "In metastatic prostate cancer, the maturation of osteoclast is quickened following CXCL1 stimulation, and this action has been shown to be blocked upon treatment with neutralizing antibodies against CXCL1." (PMID 32585812, 2020). "CXCL1 signaling may serve as a novel target for the treatment of metastatic prostate cancer-induced BCP." (PMID 24580964, 2014). "A recent study also reports the contribution of CXCR2 ligands CXCL1 and CXCL2 to osteolysis in metastatic prostate cancer." (PMID 30871004, 2019).